ATG3 (autophagy related 3)
Diseases named in the same sentence as ATG3 in open-access papers (continued):
Sharing a sentence is not in itself a finding about the gene and the disease.
infection (continued). "Accordingly, in vivo infection with MERS-CoV-MA-Δ4b increased the expression of autophagy mediators BECN1, ATG3 and LC3A." (PMID 36129908, 2022). "Relative to the expression levels observed at the time of infection (0 h post-infection), the transcripts of MAP1LC3, ATG3, and ATG12 were upregulated at 24 h post-infection and returned to basal level by 48 h post-infection." (PMID 36298785, 2022). "The expression levels of ATG1, ATG3, and ATG8 were upregulated in R. chinensis after infection with SM1." (PMID 35323524, 2022). "Inhibition of LC3 lipidation in ASFV infected cells is different to that observed after infection by with vaccinia virus where aberrant lipidation of LC3 is promoted by direct conjugation between ATG12 and ATG3." (PMID 34406116, 2021). "In HeLa cells, HVJ-E infection triggered autophagy through the PI3K/Akt/mTOR/p70S6K pathway in an ERK1/2-dependent manner, and the induction of autophagy promoted apoptosis in an Atg3-dependent manner." (PMID 30534001, 2018). "The reduction in Atg3 abundance driven by the infection correlated with an impairment of the lipidated form of LC3 (LC3-II) and GABARAP, particularly at 32 hours post-infection." (PMID 29300789, 2018). "Interestingly, we found that atg-3 mutants phenocopy rde-1 mutants in the transcriptional response to infection though they do not have a defect in RNAi." (PMID 39868230, 2025). "Restoration of autophagy flux was dependent on the absence of 4b during infection, since the presence of 4b in MERS-CoV-MA-WT infected cells prevented the recovery of BECN1, ATG3 or LC3A mRNA levels." (PMID 36129908, 2022). "When autophagy in MRC5 was chemically inhibited, infection with MERS-CoV-MA-WT did not induce further changes in BECN1, ATG3 or LC3A mRNA levels, as compared to non-treated cells (WT columns)." (PMID 36129908, 2022). "As neither ATG3 nor LC3 lipidation were found to be required for productive infection, it was suggested that VACV might disrupt autophagy through aberrant LC3 lipidation and ATG12-ATG3 conjugation." (PMID 38709216, 2024).
bacterial infection (3 papers, 2018 to 2023). "The pro-bacterial infection effect of pol-miR-155 is probably due to repressed autophagy as a result of inhibition of ATG3 expression." (PMID 37239318, 2023).
ATG3 also shares sentences with these, for which no sentence is quoted: lymphoma (2 papers); breast tumors (1); colorectal tumors (1); erythroleukemia (1); esophageal carcinoma (1); gallbladder cancer (1); lung (1); lung adenocarcinoma (1); lymph node metastasis (1); metabolic disorders (1); myelodysplastic syndrome (1); myeloma (1); nasal polyps (1); nasopharyngeal carcinoma (1); Obesity (1); prostate tumor (1); pulmonary arterial hypertension (1); pulmonary TB (1); skin squamous cell carcinoma (1); thymic epithelial tumors (1); thyroid cancer (1); tongue cancer (1); triple-negative breast carcinoma (1); viral disease (1).